OPALIN (oligodendrocytic myelin paranodal and inner loop protein)
Description:
Central nervous system-specific myelin protein that increase myelin genes expression during oligodendrocyte differentiation. Promotes oligodendrocyte terminal differentiation.
Synonyms: HTMP10; TMEM10; TMP10
Tractability: Antibody: UniProt places it where antibodies can reach, with medium confidence; UniProt predicts a signal peptide or a membrane-spanning region; its Gene Ontology location is reachable by antibodies, with medium confidence.
Gene: Protein-coding gene on chromosome 10 (96,343,216 to 96,359,365, reverse strand). Ensembl gene ENSG00000197430.
Subcellular location: Cell membrane
Gene Ontology:
Biological process: regulation of oligodendrocyte differentiation
Cellular component: Golgi apparatus; cell-cell contact zone; plasma membrane
Genetic constraint (gnomAD): Loss-of-function variants: 12 observed, 15.23 expected, observed/expected ratio (o/e) 0.79, 90% interval 0.5 to 1.28. The upper end of that interval is the gene's LOEUF score, 1.28, which puts it in group 5 of 6, group 1 being the genes least tolerant of losing a copy. Missense variants: 140 observed, 144.19 expected, observed/expected ratio (o/e) 0.97, 90% interval 0.85 to 1.12. Synonymous variants: 49 observed, 55.68 expected, observed/expected ratio (o/e) 0.88, 90% interval 0.7 to 1.12.
Homologues: Orthologues: chimpanzee OPALIN (100% identical), macaque OPALIN (95% identical), dog OPALIN (86% identical), mouse Opalin (78% identical), rabbit OPALIN (77% identical), rat Opalin (77% identical), pig OPALIN (74% identical).
Diseases named in the same sentence as OPALIN in open-access papers:
OPALIN is named in the same sentence as 13 diseases in open-access papers, as found by Europe PMC text mining. Sharing a sentence is not in itself a finding about the gene and the disease. The quoted sentences say what the papers report.
glioblastoma (1 paper, 2025). The most malignant astrocytic tumor (WHO grade IV). "In glioblastoma, OPALIN, LTF, IL2RA, and SLC17A7 were implicated in Temozolomide resistance through pathways related to epithelial differentiation and angiogenesis." (PMID 41020875, 2025). "In glioblastoma treated with Temozolomide, the models prioritized OPALIN, LTF, IL2RA, and SLC17A7 as candidate resistance related genes." (PMID 41020875, 2025).
glioma (1 paper, 2020). A benign or malignant brain and spinal cord tumor that arises from glial cells (astrocytes, oligodendrocytes, ependymal cells). "In addition, GABRD and SYT1 are implicated in gliomagenesis, and all other core genes, with the exception of OPALIN, have been reported to play a role in tumor-related diseases, including glioma." (PMID 33718116, 2020).
tumor (1 paper, 2022). "The oligodendrocyte marker genes OPALIN, MAG, and KLK6 are up-regulated in tumor cells and down-regulated in the periphery." (PMID 35327982, 2022).
OPALIN also shares sentences with these, for which no sentence is quoted: astrocytoma (1 paper); demyelinating disorders (1); depression (1); epilepsy (1); fucosidosis (1); infection (1); multiple sclerosis (1); Parkinson disease (1); Spastic paraplegia (1); temporal lobe epilepsy (1).